PROX1 (prospero homeobox 1)
Diseases named in the same sentence as PROX1 in open-access papers (continued):
Sharing a sentence is not in itself a finding about the gene and the disease.
gastric cancer (continued). "We studied MMP14 and PROX1 expression levels in tissue samples compared with clinical data, and determined the MMP14 and PROX1 expression levels in gastric cancer cells." (PMID 31560170, 2019). "In this study, we confirm that survival is worse among gastric cancer patients with a high MMP14 tissue expression and, for the first time, show that survival is worse particularly when PROX1 is low." (PMID 31560170, 2019). "In total, seven out of eleven gastric cancer cell lines—MKN‐28, KATOIII, MKN‐7, MKN‐74, MKN‐45, NUGC3, and OCUM‐2MD3—showed a clear inverse correlation with the MMP14 and PROX1 expression levels." (PMID 31560170, 2019). "Recent data shows that positive PROX1 expression correlates with positive lymph node metastases in CRC and gastric cancer." (PMID 27411302, 2016). "Variable levels of MMP14 expression in MKN‐7, MKN‐28, and TMK‐1 accompanied by a nearly absent PROX1 expression may indicate a functional connection between MMP14 and PROX1 in gastric cancer as well, although in AGS both MMP14 and PROX1 were expressed." (PMID 31560170, 2019). "In gastric cancer tissues, this study found a negative correlation between miR-489 and PROX1 protein expression." (PMID 28854215, 2017). "Additionally, in the immunofluorescence analysis, the MMP14 expression in MKN‐7 and MKN‐28 accompanied by a nearly absent PROX1 expression may indicate a functional connection between MMP14 and PROX1 in gastric cancer as well." (PMID 31560170, 2019).
glioma (14 papers, 2011 to 2024). A benign or malignant brain and spinal cord tumor that arises from glial cells (astrocytes, oligodendrocytes, ependymal cells). "We also performed the Kaplan-Meier analysis in 516 Lower grade glioma patients from TCGA via the R software and revealed that high relative expression of PROX1 is associated with lower survival rates." (PMID 36969058, 2023). "In high-grade gliomas, and in colorectal cancer, high PROX1 tissue expression is associated with poor patient survival." (PMID 27411302, 2016). "In the present study, we investigated the presence of PROX1 protein and its association with survival in a series of gliomas WHO grade II." (PMID 21559010, 2011). "The functional loss experiment suggested that PROX1 may regulate the biological behavior of glioma cells by regulating key protein levels." (PMID 36505874, 2022). "In conclusion, circ_0007534 may promote glioma cell proliferation, migration, invasion, inhibition of cell apoptosis, and other malignant biological behaviors through the miR-22-3p/PROX1 axis, which provides novel ideas for identifying early diagnostic and therapeutic targets of glioma." (PMID 36505874, 2022). "We have recently shown that PROX1 may act as a diagnostic marker for high-grade gliomas." (PMID 21559010, 2011). "Given the critical role of PROX1 in glioma progression and the inhibitory effect of TPL on PROX1 expression, it is possible that PROX1 play an essential role in TPL-mediated glioma inhibition." (PMID 36969058, 2023). "The publicly available clinical data of Brain Lower Grade Glioma (LGG) from The Cancer Genome Atlas (TCGA) had been screened to observe PROX1 expression." (PMID 36969058, 2023). "PROX1 has been identified as an independent prognostic factor for survival in patients with World Health Organization grade II gliomas, In high−grade malignant astrocytic gliomas, PROX1 is highly expressed." (PMID 36969058, 2023). "PROX1 is highly expressed and independently identified as the prognostic factor of grade II gliomas." (PMID 36969058, 2023). "Since Grade II gliomas exhibit a highly variable course and can transform into a more malignant phenotype at any time, the same group of researchers conducted another study in order to evaluate PROX1 as a predictive and prognostic marker in Grade-II gliomas." (PMID 35885529, 2022). "StarBase database screening and follow-up experiments verified the targeted interaction between miR-22-3p and PROX1 and that the effect of circ_0007534 on silencing glioma cells was partly based on the downregulation of PROX1." (PMID 36505874, 2022). "The role of PROX1 in lymphangiogenesis was previously shown in our previous studies using a sciatic nerve injury mouse model and mouse glioma model." (PMID 33986371, 2021). "No Prox1+ cells were observed in the normal tissues, whereas Prox1+ cells were distributed in large and small blood vessels and among capillary endothelial cells in gliomas." (PMID 31960509, 2020). "Staining for Prox1 revealed abundant LYVE1+/Prox1+ tumor cells and lymphatic endothelial cells in gliomas." (PMID 31960509, 2020). "Together with our previous study in low-grade gliomas, we propose that PROX1 is a clinically valuable biomarker to predict the course of disease for these patients." (PMID 27626492, 2016). "We have previously shown that the proportion of PROX1 expressing tumor cells correlates with the malignancy grade of gliomas, and that increased PROX1 protein expression predicts shorter survival for patients with diffuse low-grade gliomas." (PMID 27626492, 2016). "Recent studies have demonstrated that higher PROX1 protein expression in gliomas is indicative of a more aggressive phenotype." (PMID 24797520, 2014). "Our results suggest that PROX1 protein expression is a new molecular marker for survival in patients with grade II gliomas." (PMID 21559010, 2011).
glioma (continued). "The majority of the LGG in the present study contained relatively few PROX1 expressing cells, consistent with our previous findings that PROX1 protein expression was generally higher in high-grade than in low-grade gliomas." (PMID 21559010, 2011). "In conclusion, the present findings support our previous work showing that higher PROX1 protein expression in gliomas reflects a more malignant phenotype." (PMID 21559010, 2011). "HIF‐1α+ Prox1+ cells were widely distributed within the glioma specimens." (PMID 31960509, 2020). "Thus, it seems that the prognostic impact of PROX1 in low-grade gliomas is also pathway-dependent, consistent with our findings in high-grade astrocytomas." (PMID 27626492, 2016). "Further studies on the functional role of PROX1 as a biomarker in gliomas are warranted." (PMID 21559010, 2011). "PROX1 is a novel predictor of survival for grade II gliomas." (PMID 21559010, 2011). "The aim of this study was to address the prognostic value of PROX1 in grade II gliomas." (PMID 21559010, 2011). "Our study also promotes PROX1 as a prognostic marker for WHO grade II gliomas." (PMID 21559010, 2011). "However, EdU+PROX1+ newborn GCs were observed in surgically resected young and adult human hippocampi from patients diagnosed with epilepsy, temporal lobe lesions, or suspected low-grade glioma after in vitro culture." (PMID 38607670, 2024). "However, PROX1 enables the glioma cells to regain the migratory capacity." (PMID 36969058, 2023). "Although still consistent with the histopathological diagnosis of WHO grade II glioma, such tumours displaying a high proportion of PROX1-positive cells may be further advanced on the evolution to anaplastic gliomas compared with tumours with few PROX1 expressing tumour cells." (PMID 21559010, 2011). "have shown that High-grade gliomas (grades III and IV) have a higher expression of PROX1, and PROX1 can be used as a molecular marker for the diagnosis of astrocytic gliomas." (PMID 36969058, 2023). "In summary, we observed up‐regulated co‐expression of Prox1 and HIF‐1α in gliomas as well as the differentiation of nestin+ tumor stem cells into LYVE‐1+ lymphatic endothelial cells that formed lymphatic vessels." (PMID 31960509, 2020). "The present immunohistochemical analysis revealed upregulation of Prox1 and HIF‐1α in some glioma tissues as well as the differentiation of nestin+ tumor stem cells into LYVE‐1+ lymphatic vessels." (PMID 31960509, 2020). "Prox1+/LYVE‐1+ cells were distributed in some lymphatic vessels as well as among vascular endothelial cells and glioma cells." (PMID 31960509, 2020). "Clonal analyses in mouse brains suggest that glioma originate from NG2+ OPCs, and glioma cells are known to express Prox1." (PMID 26709696, 2015). "Specimens from seven glioma cases were analyzed by immunohistochemical staining for CD34, lymphatic endothelial hyaluronic acid receptor 1 (LYVE‐1), prospero‐related homeobox 1 (Prox1), nestin, and hypoxia‐inducible factor 1α (HIF‐1α)." (PMID 31960509, 2020). "Therefore, it can be concluded that rapid proliferation of glioma cells triggers hypoxia within the tumor cells, activating downstream genes including HIF‐1α and Prox1 and leading to tumor cell differentiation and expression of LYVE‐1." (PMID 31960509, 2020). "Instead, we found that PROX1 is a predictor for survival in the group of high-grade 1p19q non-codeleted astrocytomas that are IDH-mutant and predominate in younger patients with a prior history of low-grade gliomas." (PMID 27626492, 2016). "Together with our previous studies in low-grade gliomas, we conclude that PROX1 is a pathway-specific biomarker for IDH-mutant, 1p19q non-codeleted astrocytomas that may be used to identify high-risk patients." (PMID 27626492, 2016). "Notably, many Prox1+ HIF‐1α+ cells were distributed in gliomas but not seen in normal brain tissue." (PMID 31960509, 2020).
glioma (continued). "High-grade gliomas (III and IV) showed strong positivity for PROX1, while grade II and I tumors or non-neoplastic brain tissue expressed significantly lower PROX1 levels." (PMID 35885529, 2022). "Interestingly, data extracted from TCGA displayed a statistically significant correlation between PROX1 gene expression and survival for patients with IDH-mutant, 1p19q non-codeleted low-grade astrocytomas, but not with IDH-wildtype or 1p19q codeleted low-grade gliomas." (PMID 27626492, 2016).
pancreatic cancer (14 papers, 2010 to 2025). "On the other hand, PROX1 expression is down-regulated in pancreatic cancer tissues, and loss of PROX1 function is associated with decreased patient survival." (PMID 24797520, 2014). "Their results showed that miR-934 upregulation is related to the prognosis of pancreatic cancer patients and that the increase in cellular malignant characteristics caused by miR-934 overexpression can be reversed by inhibiting the expression of PROX1." (PMID 34721576, 2021). "In pancreatic cancer, the expression of PROX1 is downregulated, while, conversely, PROX1is abundant in the normal exocrine pancreas." (PMID 35885529, 2022). "Although PROX1 mRNA was slightly down-regulated in pancreatic carcinomas, immunofluorescence revealed variable PROX1 protein expression in pancreatic carcinomas." (PMID 24797520, 2014). "PROX1 is found to be slightly reduced in pancreatic cancer tissue." (PMID 35885529, 2022). "The IHC staining of PROX1 could help in the future with the differentiation of pancreatic carcinomas." (PMID 35885529, 2022). "Because of the limitations of IHC, we can only speculate, whether cytoplasmic PROX1 in pancreatic tumor tissue is in active or inactive form." (PMID 27411302, 2016). "For example, bone marrow-derived macrophages (BMDMs) can express LYVE1, PROX1, and PDPN, and form lymphatic-like structures in vitro and LYVE1 + PROX1 + PDPN + bone marrow derived cells undergo lymphatic vascular mimicry during neo-lymphangiogenesis in VEGFC-expressing pancreatic tumors in mice." (PMID 38218743, 2024). "In pancreatic cancer, differential hydroxymethylation of genes related to pancreas development or function (GATA4, GATA6, PROX1, ONECUT1, MEIS2), and cancer pathogenesis (YAP1, TEAD1, PROX1, IGF1) have also been shown to reliably identify pancreatic cancer from peripheral blood samples." (PMID 36835649, 2023).
bladder cancer (12 papers, 2016 to 2025). "PROX1 promotor hypermethylation was also found to be associated with lymphatic metastasis in bladder cancer." (PMID 37627900, 2023). "As previously discussed, lncRNAs can also directly bind genomic DNA as triplex-DNA, as does the LNMAT2 lncRNA at the PROX1 TF promoter, where it also physically associates with hnRNPA2/B1 to promote PROX1 transcriptional activation in bladder cancer." (PMID 37444543, 2023). "It has been reported that exosomal long noncoding RNA LNMAT2 upregulates PROX1 in HLECs to promote bladder cancer lymphangiogenesis and LNM." (PMID 39866224, 2025). "Yet another mechanism by which an lncRNA is able to regulate PROX1 expression has been identified in the context of bladder cancer." (PMID 37407839, 2023). "Indeed, PROX1 was one of the identified target genes that were hypermethylated in a DNA screening of urine from patients with bladder cancer." (PMID 27626492, 2016). "A 5-gene panel (VAX1, CFTR, KCNV1, PROX1, and TAL1) had an 88.7% sensitivity and an 87.3% specificity for the diagnosis of bladder cancer." (PMID 37627900, 2023). "Bladder cancer cells secrete exosomes containing LncRNA LNMAT2 and upregulate PROX1 expression to promote lymphangiogenesis and lymphatic metastasis." (PMID 37915049, 2023). "The methylation frequency of eight genes (VAX1, ECEL1, KCNV1, LMX1A, PROX1, SLC6A20, TAL1, and TMEM26) was significantly higher in the urine of bladder cancer patients as compared to that of normal controls." (PMID 37627900, 2023). "LNMAT2 was found to bind to the prospero homeobox 1 (PROX1) promoter by inducing H3K4 trimethylation, which enhanced PROX1 transcription, thus promoting lymphangiogenesis and lymph node metastasis in bladder cancer." (PMID 33869048, 2021). "Interestingly, the LNMAT2-mediated mechanism of PROX1 activation is VEGF-C-independent, explaining why approximately 20% of bladder cancers with LN metastasis have low VEGF-C expression." (PMID 37407839, 2023). "Bladder cancer cell-derived EVs can deliver the lncRNA LNMAT2, which promotes lymphangiogenesis and LNM by recruiting hnRNPA2B1 and increasing the H3K4 trimethylation level in the prospero homeobox 1 (PROX1) promoter." (PMID 34552874, 2021).
diabetes (12 papers, 2012 to 2023). "And PROX1 has been shown to be associated with diabetes and its complications in a number of studies." (PMID 32390949, 2020). "Recently, a GWA study revealed that PROX1 rs340841 is a strong susceptibility locus of early onset of diabetes with variations depending on ethnicity." (PMID 32390949, 2020). "In addition, Prox1 has been reported to have a strong association with diabetes." (PMID 28846711, 2017). "Several PROX1 variants have been associated with a risk for alterations in glucose and lipid metabolism, but not with monogenic diabetes or insulinomatosis." (PMID 35406570, 2022). "Furthermore, several genes involved in the endocrine specification and diabetes development were significantly downregulated, such as HES1, INSM1, HNF1A, NEUROD1, NGN3, NKX2.2, GIPR, MNX1, PROX1, TCF7L2, and HHEX." (PMID 33473118, 2021).
lymphangioma (11 papers, 2007 to 2025). A benign lesion composed of dilated lymphatic channels. "Lymphangiomas and hemangiomas (mainly venous and spindle-cell subtype), as well as the vast majority of Kaposi sarcomas and reti- and kaposiform hemangioendotheliomas, are associated with the overexpression of PROX1." (PMID 35885529, 2022). "In case 1, immunohistochemical staining for CD31 and prospero homeobox 1 (Prox1) was performed to distinguish the conditions from chronic lymphocytic enteritis, lymphangioma, and lymphangiectasis." (PMID 38783305, 2024). "Immunohistochemical markers used in the diagnosis of lymphangioma are lymphatic vessel endothelial receptor-1, vascular endothelial growth factor-3, monoclonal antibody D2-40 and prox-1." (PMID 25866696, 2015). "With immunohistological methods, we have recently been able to identify VEGFR-3 and Prox1 in CD31-positive LECs of lymphangiomas." (PMID 17584927, 2007). "LECs from foreskin and lymphangioma had an almost identical pattern of lymphendothelial markers such as podoplanin, Prox1, reelin, cMaf and integrin-α1 and -α9." (PMID 17584927, 2007). "Double staining with Prox1 and CD31 is the most reliable method for characterizing lymphangioma endothelial cells." (PMID 27843456, 2016). "Lymphatic differentiation in KS is a well-known distinctive feature of this tumor type (even though it is absent in lymphangioma and kaposiform HE) and occurs due to the regulation of Prox-1, a key regulator of lymphatic differentiation, by HHV8." (PMID 31252633, 2019). "While hemangiomas exhibit dilated, blood-filled vascular channels lined by bland endothelial cells and stain positively for CD31, CD34, and FLI-1 (but are typically GLUT-1 negative in adults), lymphangiomas show similar spaces filled with proteinaceous fluid and are D2-40 and PROX1 positive." (PMID 40428263, 2025).